SDHA (succinate dehydrogenase complex flavoprotein subunit A)
Diseases named in the same sentence as SDHA in open-access papers (continued):
Sharing a sentence is not in itself a finding about the gene and the disease.
Lynch syndrome (1 paper, 2025). An autosomal dominant hereditary neoplastic syndrome characterized by the development of colorectal carcinoma and a high risk of developing endometrial carcinoma, gastric carcinoma, ovarian carcinoma, renal pelvis carcinoma, and small intestinal carcinoma. "Five cases exhibited combinations of HBOC and endocrine or Lynch syndrome genes (e.g., SDHAF2, SDHA, MSH6)." (PMID 40943312, 2025).
major depressive disorder (1 paper, 2024). An episode of depression lasting two or more weeks without an intervening episode of mania. "In the TCA cycle, CS, IDH3G, SDHA, and SDHB were upregulated in major depressive disorder and downregulated in ketosis, whereas SUCLG2 was downregulated in both." (PMID 39125835, 2024).
malaria (1 paper, 2020). Malaria is a serious and sometimes fatal disease caused by a parasite that commonly infects a certain type of mosquito which feeds on humans. "All human proteins in this cluster were known to be drug targets and there were 19 associations of these five human proteins (SUCLG1, SDHA, SDHB, SDHC, and SDHD) and five malaria proteins (PVX_096130, PVX_123265, PVX_003675, PVX_113540, and PVX_003575)." (PMID 32075230, 2020).
microcephaly (1 paper, 2018). A congenital or acquired developmental disorder in which the circumference of the head is smaller than normal for the person's age and sex. "The derivative chromosome results in a partial monosomy of 5p15.2 → pter, producing haploinsufficiency of the SDHA (5p15.33) and SEMA5A (5p15.31) genes that have been related to psychomotor retardation, microcephaly, pachygyria and microgyria." (PMID 29760780, 2018).
nasal polyps (1 paper, 2018). "In intact RNA, they found that the genes for hydroxymethyl-bilane synthase (HMBS) and succinate dehydrogenase complex, subunit A (SDHA) in CRS, and ACTB and TBP in nasal polyps were the most stable among nine candidate reference genes analysed using geNorm." (PMID 29371606, 2018).
pancreatic neuroendocrine tumor (1 paper, 2022). Pancreatic endocrine tumor, also known as pancreatic neuroendocrine tumor (PNET), describes a group of endocrine tumors originating in the pancreas that are usually indolent and benign, but may have the potential to be malignant. "Here we report co-occurrence of germline pathogenic variants in both VHL and SDHA genes in a patient who presented with pancreatic neuroendocrine tumor." (PMID 35875079, 2022).
parathyroid disease (1 paper, 2022). "Using NGS, we identified three pathogenic variants in two genes (CDC73 and MEN1), 10 likely pathogenic variants in six genes (CASR, CDC73, LRP5, MEN1, SDHA, and VHL), and 39 non-synonymous VUS variants that could be related to parathyroid disease." (PMID 35586626, 2022).
phyllodes tumor (1 paper, 2025). A benign, borderline, or malignant fibroepithelial neoplasm arising from the breast and rarely the prostate gland. "Consistent with previous findings, this study revealed a positive correlation between tumor grade and SDHA expression in the tumor stroma of phyllodes tumors in the breast." (PMID 40119440, 2025).
schizophrenia (1 paper, 2024). A major psychotic disorder characterized by abnormalities in the perception or expression of reality. "The gene SDHA showed a discordant pattern (i.e., it was upregulated in schizophrenia but downregulated in ketosis)." (PMID 39125835, 2024). "In the TCA cycle, the genes CS, SDHA, and SUCLG2 were upregulated in schizophrenia but downregulated in ketosis, and SDHB was downregulated in both." (PMID 39125835, 2024).
schwannoma (1 paper, 2024). A benign, usually encapsulated slow growing tumor composed of Schwann cells. "Schwannoma had the known heterozygous pathogenic variant (p.V333Sfs*15) but no second hit in SDHA." (PMID 38885448, 2024).
Sepsis (1 paper, 2024). Sepsis is defined as life-threatening organ dysfunction caused by a dysregulated host response to infection. "In LPS-stimulated macrophages, overexpression of SIRT3 through SDHA deacetylation, mitigates sepsis-associated aerobic glycolysis.The role of SIRT4 in inflammatory immune responses is not entirely clear yet." (PMID 38690282, 2024). "SIRT3 further enhances the efficiency of the oxidative phosphorylation chain by deacetylating the pivotal enzyme SDHA, mitigating electron leak and consequently reducing the generation of ROS during sepsis and ischemia-reperfusion." (PMID 38690282, 2024).
Stroke (1 paper, 2021). Sudden impairment of blood flow to a part of the brain due to occlusion or rupture of an artery to the brain. "The significant increase of NRF1 expression level was 20% (p < 0.01), that of TFAM was 50% (p < 0.01), that of NDUFV2 was 20% (p < 0.01), that of SDHA was 50% (p < 0.01), and that of VEGF was 40% (p < 0.01), compared to the Stroke + Saline group." (PMID 33806692, 2021). "In our stroke model, we observed a pronounced short-term PGC-1α activation, evidenced by a significant upregulation of PGC-1α-dependent proteins: NRF1, TFAM, catalytic subunits of the substrate-binding sites of the respiratory chain (NDUFV2 and SDHA), VEGF, and SYP." (PMID 33806692, 2021).
urinary tract infection (1 paper, 2016). "If so, it is possible that drugs designed to inactivate the enzymes encoded by gdhA, gnd, pykF, sdhA, and zwf might be effective in limiting recurrent urinary tract infection." (PMID 27303698, 2016).
virus infection (1 paper, 2015). "The high-light-adapted PE A1-OS and A1-MS strains also have unique genes involved in the TCA cycle (sdhA) and virus infection (Type III CRISPR/cas array), which may be indicative of uncharacterized environmental realities of the high-light-adapted strains compared to the low-light-adapted strains." (PMID 26157428, 2015).
tumor (135 papers, 2007 to 2026). "This research provides initial direct evidence suggesting that the loss of SDH activity plays a tumor-promoting role in HCC models by inducing the accumulation of cellular succinate (SDHA/B in HCC)." (PMID 40119440, 2025). "They showed that inhibiting class I glucose transporters was effective in inhibiting tumor growth in patient-derived xenograft models of SDHA-deficient tumors." (PMID 40141095, 2025). "Specifically, higher transcriptional expression of SLC2A3 and SDHA was associated with an increased likelihood of having an active tumor at the last contact or time of death." (PMID 40141095, 2025). "For those without identified germline sequencing variants, particularly those with an SDHA mutation on mutational tumor testing, SDHA full gene analysis should be conducted." (PMID 39927693, 2025). "According to our results, the joint assessment of SLC2A3 and SDHA transcriptional expression allowed us to define a group of patients with an elevated risk of local tumor recurrence after treatment with RT or CRT." (PMID 40141095, 2025). "Assessing these differences for each individual gene in association with tumor location shows that proportionally more HNPs were reported for European patients with PVs in SDHA, SDHB, SDHC, and SDHD than for Asian patients." (PMID 38481600, 2024). "Their findings suggest that SDHA mutations result in the loss of SDHA protein expression, subsequently initiating tumor development." (PMID 39765842, 2024). "The estimated lifetime tumor risk for individuals with an SDHA pathogenic variant continues to be revised as new data is disseminated." (PMID 38770192, 2024). "We would also recommend detailed discussion of symptoms relating to SDHA-associated tumours, both as an adjunct or alternative to surveillance." (PMID 35260474, 2023). "Studies of SDHA PGV carriers suggest that lifetime penetrance for SDHA-associated tumours is low, particularly when identified outside the context of a family history." (PMID 35260474, 2023). "Most SDHA PGV carriers present with an apparently sporadic tumour, but often the pathogenic variant has been inherited from parent who has the variant, but has not developed any clinical features." (PMID 35260474, 2023). "Routine pituitary imaging is not recommended (see also Recommendation 4: surveillance for SDHA PGV carriers affected with SDHA-associated tumours section)." (PMID 35260474, 2023). "Another recent study indicated that tumor cells in SDHA-deficient RCC showed negativity for both SDHA and SDHB, while RCC caused by defects in the SDHB, SDHC, or SDHD genes only showed negativity for SDHB." (PMID 37367052, 2023). "Due to the reported low penetrance and few reports of familial cases we suggest consideration of offering predictive testing only to first-degree relatives of an affected proband, unless there is a wider family history of SDHA-associated tumours." (PMID 35260474, 2023). "SDHA is a tumour suppressor gene and a second hit through loss of the wild-type allele can be observed in GISTs from germline variant carriers." (PMID 33854214, 2021). "Immunohistochemistry and molecular analysis of the wtGISTs revealed loss of SDHB expression and loss of the wild-type SDHA allele in tumour material." (PMID 33854214, 2021). "Both had the same SDHA mutation (c.1945_1946delTT) in the tumor tissue; therefore, they are the first reported patients to have PGLs with somatic SDHA genomic alteration." (PMID 33031286, 2020). "The staining results showed loss or decreased SDHB expression but preserved SDHA expression in the examined neoplasms, as compared with adjacent normal tumor tissues." (PMID 33031286, 2020). "In this study, we first reported the correlation between SDHA mutation and tumor stage, indicating its potential predictive value." (PMID 33219256, 2020). "In this study, combined RNA and chromatin immunoprecipitation (ChIP) sequencing analysis, we linked the anti-tumor effect of chidamide to enhanced expression of SDHA." (PMID 33014881, 2020).
tumor (continued). "The third patient (SNP-107, PGL) with a germline SDHA mutation who after 7 cycles had a 56% reduction in target tumour volume, subsequently developed new lesions after 10 cycles of sunitinib." (PMID 31105270, 2019). "Because of the loss of SDHB protein observed in tumor versus normal tissue, we considered the possibility of somatic alterations to the paternal SDHA wild‐type allele." (PMID 30680959, 2019). "Biallelic inactivation (typically resulting from one inherited and one somatic event) at one of the four genes encoding the SDH complex (SDHA/B/C/D) is the most common cause for SDH deficient (dSDH) tumours." (PMID 30589099, 2019). "SDH-deficient tumours are most commonly associated with a germline SDH subunit gene (SDHA/B/C/D) mutation but can also be associated with epigenetic silencing of the SDHC gene." (PMID 31308404, 2019). "For comparison, SDHB staining in endothelial cells from the SDHA wild‐type ccRCC tumor and SDHA‐mutated GIST tumor is shown in S1C and S1D, respectively." (PMID 30680959, 2019). "Alhough the SDHA/B/C/D subunits form a single complex, mutations in different genes are associated with relative differences in susceptibility to specific tumor types." (PMID 28546994, 2017). "The clinical spectrum of SDHA‐associated neoplasia differs from that of germline mutations in other SDH‐subunits." (PMID 28546994, 2017). "SDHA sequence analysis on a PGL from a patient with a c.1753 C>T variant (p.Arg585Trp) demonstrated partial loss of the wild‐type allele in the tumor DNA consistent with pathogenicity." (PMID 28546994, 2017). "In conclusion, this review of published SDHA mutations and reporting of variants from our novel cohort, should aid interpretation of genetic testing results in patients with relevant tumor types." (PMID 28546994, 2017). "Fortunately, SDHA immunohistochemistry has proved useful in identifying tumours that are likely to contain SDHA mutations." (PMID 26273102, 2015). "The WT GIST associated with a germline SDHA mutation showed complete loss of both SDHA and SDHB protein, while the tumor with a somatic, heterozygous SDHA mutation showed significant decreased in SDHA immuno-expression, as well as complete loss of SDHB." (PMID 22974104, 2012). "Of note, the SDHA sequence electropherogram of the normal DNA revealed equivalent proportion of the wild-type and the mutated allele (T), whereas tumor DNA contained predominantly the mutated allele (T), indicating relative loss of the wild-type SDHA allele." (PMID 22974104, 2012). "Testing of tumour-derived DNA identified an SDHA variant, later confirmed of germline origin." (PMID 41635891, 2026). "In humans, SDHA mutations cause neurodegeneration, muscle weakness and tumor formation." (PMID 40904733, 2025). "To unravel the mitochondrial role in concurrent GIST and NB, we assessed SDHA expression in recurrent tumor tissues and adjacent ones, revealing stark SDHA loss in tumors alongside up-regulated subunits of mitochondrial complex I (ND5), complex III (UQCRC2), complex IV (CO1), and complex V (ATP5a)." (PMID 39464303, 2024). "Additionally, the loss of SDHA expression in tumors consistently predicts the presence of SDHA mutations in tumor cells and associated germline material." (PMID 36980917, 2023). "The presence of a germline mutation accompanied by loss of the allele in the tumor is presumed also in the two patients for which germline DNA was not available; based on tumor sequencing, the data revealed the presence of homozygous missense SDHA mutations." (PMID 36980917, 2023). "Should there be immunohistochemical evidence of SDHB/SDHA loss, or suggestive family history, then we would recommend surveillance and predictive testing be undertaken in line with the recommendations for patients with SDHA-associated tumours (see recommendations 4–6 below)." (PMID 35260474, 2023).
tumor (continued). "Thus, mutations to the SdhA subunit most often result in mitochondrial disease phenotypes, whilst mutations to the other subunits SdhB-D more commonly result in tumour formation." (PMID 35563430, 2022). "Specifically, these mutations are located on five tumor suppressors (SDHA, RB1CC1, PTCH1, DMBT1, BCR) and eight proto-oncogenes (MERTK, CSF1R, MYB, ROS1, PCM1, FGFR2, MYH11, BRCC3) and have an allele frequency lower than 0.01 in the Genome Aggregation Database (GnomAD)." (PMID 33466296, 2021). "Loss of heterozygosity (LOH) analysis was performed on DNA from both tumours to support the role of the SDHA variant being causal and also investigate whether there was any evidence for the PALB2 variant contributing to tumourigenesis." (PMID 33854214, 2021). "In this tumor, additional mutations were identified in AR (A159T) and SDHA (T36I)." (PMID 32099073, 2020). "In another study, any-tumor penetrance at 40 years old among SDHA mutation carriers was 13%." (PMID 30854332, 2019). "These include size (≥5–6 cm), extra-adrenal location of the primary tumor, noradrenergic/dopaminergic biochemical phenotype, mutations of the succinate dehydrogenase A and B (SDHA/B) genes, tumor multiplicity/recurrence, and age at first presentation (<20 years)." (PMID 31597347, 2019). "Hence, SDHA epitomizes a moonlighting protein, being an enzyme that is a baseline tumor suppressor but becomes a promoter of tumor growth in the context of bioenergetic deficiency." (PMID 29880867, 2018). "However, the second WT tumor, with compound heterozygous SDHA missense mutations (c.818C > T, p.T2731I; c1357G > A, p.G453R) stains positive for SDHA, as does the third WT case, in which no SDHX mutations were detected." (PMID 23730622, 2013). "Furthermore, this tumor showed significant loss of SDHA protein expression by both western blot and IHC, suggesting a functional impact of this genetic alteration." (PMID 22974104, 2012). "Current national guidelines recommend that SDHA variants should only be considered actionable (that is, to lead to surveillance in the proband and family screening) if they are identified in individuals with a personal or family history of an SDHA-related tumour." (PMID 41635891, 2026). "Furthermore, we suggest that there should also be an increased emphasis on defining whether a rare germline SDHA variant is associated with the expected functional consequences of SDHA inactivation in the relevant tumor." (PMID 28546994, 2017). "On the other hand, SDHA has been described as a tumor suppressor because it reduces the accumulation and secretion of succinate, considered an oncometabolite." (PMID 40141095, 2025). "We performed a mass spectrometry-based drug target discovery study to identify shikonin’s unexplored targets to determine the specific mechanism by which shikonin effectively eradicates SDHA-overexpressing tumor cells." (PMID 40563592, 2025). "Germline testing is recommended for SDHA, SDHB, SDHC, and SDHD across all ages and tumor types in the setting of SDH‐deficient staining and/or when an SDHx PV is identified in the tumor." (PMID 39927693, 2025). "By analyzing the data included in The Cancer Genome Atlas (TCGA), it can be observed that the prognostic capacity of SDHA transcriptional expression depends on the tumor type." (PMID 40141095, 2025). "We observed that the BPPNM cells endogenously overexpressing SDHA showed significantly higher numbers of tumor cell colonies than the SPCA cell line with naturally very low SDHA expression or the isogenic BPPNM cell line with SDHA knockdown." (PMID 40563592, 2025). "Moving forward, we will prioritize elucidating the mechanistic aspects that promote tumor proliferation in SDHA-elevated BC cells." (PMID 40119440, 2025). "By contrast, the SDHA-KO B6 animals demonstrated significantly better tumor control than the WT B6 control-treated animals, similar to the anti-PD-1-treated WT B6 animals." (PMID 41392980, 2025).